SSTR2 (somatostatin receptor 2)
Diseases named in the same sentence as SSTR2 in open-access papers (continued):
Sharing a sentence is not in itself a finding about the gene and the disease.
sarcoidosis (3 papers, 2017 to 2025). Sarcoidosis is a multisystemic disorder of unknown cause characterized by the formation of immune granulomas in involved organs. "Western blotting confirmed the upregulated expression of SSTR2 in cases of granulomatous inflammation (sarcoidosis) of the skeletal and heart muscle, in contrast to healthy skeletal and cardiac muscle." (PMID 39518342, 2024). "Western blotting confirmed the upregulated expression of SSTR2 in cases of granulomatous inflammation (sarcoidosis) of the skeletal and heart muscle, in comparison with controls." (PMID 39518342, 2024). "In conclusion,68Ga labeled SSTR2 PET/CT seems an interesting alternative to FDG PET/CT in (cardiac) sarcoidosis, since these modalities have different imaging targets." (PMID 29782604, 2017). "Additional studies comparing these radiopharmaceuticals are needed, particularly to evaluate in which phase of sarcoidosis (acute or chronic) 68Ga labeled SSTR2 PET/CT will be more beneficial than FDG." (PMID 29782604, 2017). "At the moment, it is unclear whether SSTR2 PET/CT imaging is more beneficial in acute or chronic sarcoidosis." (PMID 29782604, 2017). "Applying this 68Ga-SSTR2 in the chronic phase (relapse/recurrence) of (cardiac) sarcoidosis seems to be a potential role, maybe combined with CMR, using hybrid PET/MRI." (PMID 29782604, 2017). "However, SRS is not always specific for NETs because SRS also detects other SSTR2-expressing tumors and non-neoplastic lesions such as sarcoidosis and rheumatoid arthritis." (PMID 41464537, 2025).
schizophrenia (3 papers, 2014 to 2020). A major psychotic disorder characterized by abnormalities in the perception or expression of reality. "Links between specific risk factors, such as maternal inflammation, and molecular alterations are critical to the development of mental illnesses, and we have identified SST and its receptor, SSTR2, as potential mediators of gestational inflammation-related risk for schizophrenia." (PMID 32029751, 2020). "We present the first rodent MIA study of cortical and striatal deficits in SST and SSTR2 gene expression that concurs with cortical SST and SSTR2 mRNA deficits found in post-mortem schizophrenia studies." (PMID 32029751, 2020). "Our novel finding of SST and SSTR2 mRNA reductions in striatum suggests that further examination of SST-related neurotransmission may be warranted in the striatum of people with schizophrenia." (PMID 32029751, 2020). "For example Beneyto and co-workers used in situ hybridization to quantify the mRNA expression levels of SST receptors subtype 1 (SSTR1) and subtype 2 (SSTR2) in dorsolateral prefrontal cortex area 9 from 23 matched pairs of subjects with schizophrenia and normal comparison subjects." (PMID 24570674, 2014).
thymoma (3 papers, 2022 to 2025). A neoplasm arising from the epithelial cells of the thymus. "Somatostatin receptor 2 (SSTR2) is expressed in some thymic epithelial tumors, particularly thymomas." (PMID 41300989, 2025). "In contrast, SSTR2 was only expressed in 15% of type A and B3 thymomas and micronodular thymomas with lymphoid stroma with expression in 5% or less of tumor cells." (PMID 35198446, 2022). "Weak expression was seen in 2 thymomas with 1% of tumor cells expressing SSTR2 and in an adenosquamous carcinoma with 5% of tumor cells expressing SSTR2." (PMID 35198446, 2022). "Despite our findings of low SSTR2 expression in thymomas, literature has suggested that thymomas may show response to treatment with octreotide." (PMID 35198446, 2022). "Furthermore, among those expressing SSTR2, there was a trend of higher expression of SSTR2 (≥ 50%) in thymic carcinomas (10 of 19, 52.6%) and TNETs (2 of 4, 50%) than in thymomas (0 of 6) (p=0.07)." (PMID 35198446, 2022). "Although DOTATATE PET scans are part of the clinical workup of some TET, specifically TNETs and octreotide treatment has been used in a subset of TET including thymomas, thymic carcinomas, and TNETs, SSTR2 expression has only been studied in small case series or case reports." (PMID 35198446, 2022). "While this appears to be a new finding it may, at least in part, be because patients with thymic carcinomas and TNETs were younger than patients with thymoma and SSTR2 was more commonly expressed in thymic carcinomas and TNETs than in thymomas." (PMID 35198446, 2022). "Indeed, significantly more thymic carcinomas and TNETs expressed SSTR2 than thymomas." (PMID 35198446, 2022). "SSTR2 expression was more common among thymic carcinomas (57.6%) and TNET (57.1%) as compared to thymomas (15.0%, p<0.001)." (PMID 35198446, 2022). "Also, SSTR2 expression in ≥ 50% of tumor cells trended to be more common in thymic carcinomas when compared to TNET and thymoma (p=0.056)." (PMID 35198446, 2022). "While these studies did not investigate the expression of SSTR2 in the tumor tissue, conceivably thymomas did express SSTR2 given the positive octreotide scans and the response to octreotide treatment in a small subset of patients." (PMID 35198446, 2022). "SSTR2 expression was identified in 29 (of 80, 36.3%) TET including 2/2 (100%) small cell carcinomas, 2/5 (40.0%) atypical carcinoid tumors, 16/23 (69.6%) squamous cell carcinomas, 2/2 (100%) lymphoepithelial carcinomas, 1/1 (100%) adenosquamous carcinoma, and 6/40 (15.0%) thymomas." (PMID 35198446, 2022). "However, since tissue was not examined for SSTR2 expression in these thymomas it remains unclear whether SSTR2 was expressed in thymocytes, tumor cells or both." (PMID 35198446, 2022). "Furthermore, because none of the studies disclosed how many patients had undergone octreotide scan before patients were selected for these trials the incidence of SSTR2 expression in thymomas could not be estimated." (PMID 35198446, 2022).
thyroid tumor (3 papers, 2020 to 2022). A benign or malignant neoplasm affecting the thyroid gland. "The study found that the expression of somatostatin receptor 2 (SSTR-2) in normal thyroid tissue and thyroid tumour tissue is different." (PMID 32297029, 2020). "SSTR-2 expression has been shown to be substantially prevalent in the thyroid, both in the normal tissue as well as in thyroid tumors." (PMID 33551992, 2020). "These “fourth-generation analogs” have been reported to show very high affinity for SSTR2, SSTR3, and SSTR5 and intermediate-high affinity for SSTR4, which possibly make them good candidates for thyroid tumor cells that express high levels of SSTR3 or 5, despite low expression of SSTR2." (PMID 35453992, 2022).
adenovirus infection (2 papers, 2013 to 2016). "Three days after adenovirus infection, the animals were injected via a marginal ear vein with 111In-octreotide, which binds SSTR2." (PMID 26983635, 2016).
B-cell NHL (2 papers, 2021 to 2024). "In IHC analysis, the B-cell non-Hodgkin lymphoma was the only tumor to demonstrate a positivity for SSTR2 presence (20%) with an intensity of SSTR2 (grade of 2), which explains its weak tracer uptake in DOTATOC PET/CT." (PMID 39123352, 2024). "Recently, one pediatric HL case was reported to co-express mRNA for all five SSTR subtypes (SSTR1-5) and in a small cohort of aggressive nasopharyngeal B-cell NHL, 40% of the 15 cases were SSTR2 positive." (PMID 34307181, 2021).
breast tumors (2 papers, 2013 to 2023). "Several other studies have also reported SSTR2 to be the most abundant SSTR subtype expressed in breast tumours." (PMID 38203605, 2023). "SSTR2 expression in breast tumour tissue was also found to be ubiquitous." (PMID 38203605, 2023). "However, SSTR2 is the prominent receptor subtype expressed ubiquitously and abundantly in breast tumor tissues and cancer cells." (PMID 24059654, 2013).
carcinoid syndrome (2 papers, 2016 to 2024). "Given their antitumor effects, somatostatin analogs such as octreotide and lanreotide (both are potent SSTR2 agonists but notably spare SSTR1) have been approved to treat gastroenteropancreatic NE tumors and carcinoid syndrome." (PMID 39352383, 2024).
Cirrhosis (2 papers, 2013 to 2018). A chronic disorder of the liver in which liver tissue becomes scarred and is partially replaced by regenerative nodules and fibrotic tissue resulting in loss of liver function. "As shown by immunohistochemical staining (IHC), Western blot and real-time PCR, SSTR-2 expression was up-regulated in the cirrhosis group compared with that in the control group." (PMID 30038293, 2018). "The present data revealed a wide range of SSTR2 and 5 expression in the tumor and cirrhosis samples." (PMID 24137418, 2013). "Furthermore, SSTR2 and 5 mRNA expression was also quantified in paired liver cirrhosis tissues to evaluate the expression of SSTR2 and 5 in tumor and cirrhosis tissues." (PMID 24137418, 2013).
colorectal NET (2 papers, 2021 to 2024). "Previous studies demonstrated that SSTR2 expression in a small cohort of rectal NETs (range 3–13 patients) and the majority of them were included as a component of left colon or colorectal NET cohorts." (PMID 38374188, 2024).
Cushing syndrome (2 papers, 2021 to 2023). Cushing's syndrome (CS) encompasses a group of hormonal disorders caused by prolonged and high exposure levels to glucocorticoids that can be of either endogenous (adrenal cortex production) or exogenous (iatrogenic) origin. "Together with the findings of the current study, these data suggest that either a lack or an excess of glucocorticoids may lead to abnormal SSTR2 expression (upregulation in adrenal insufficiency and downregulation in Cushing syndrome)." (PMID 35058882, 2021).
ectopic ACTH syndrome (2 papers, 2013 to 2021). "A clinical report of two patients with ectopic ACTH syndrome treated with mifepristone noted upregulation of SSTR2 on diagnostic imaging." (PMID 35058882, 2021). "On the other hand, SSTR2-5 also involved in ACTH secretion, thus its agonist could be used as a potential therapeutic in ectopic ACTH syndrome." (PMID 23667519, 2013). "This downregulation by glucocorticoids might explain not only the lack of efficacy of SSTR2-targeting somatostatin analogs in patients with Cushing disease but also their partial effect in patients with ectopic ACTH syndrome." (PMID 35058882, 2021).
head and neck cancer (2 papers, 2022 to 2024). A primary or metastatic malignant neoplasm affecting the head and neck. "For example, in head and neck cancer, we have found multiple signaling axes significantly associated to higher survival, such as SSTR2-SST, RXFP3-INSL5, and RXFP1-RLN3." (PMID 38723607, 2024). "For example, in head and neck cancers, we found significant correlation of higher survival and higher expression of the SSTR2-SST, RXFP3-INSL5, and RXFP1-RLN3 signaling axis, which all share similar coupling profiles (e.g., Gq/11, particularly GNA14, as well as Gi/o)." (PMID 38723607, 2024).
hemangioma (2 papers, 2025 to 2026). A benign vascular lesion characterized by the formation of capillary-sized or cavernous vascular channels. "Histopathology was conclusive of OLIG2 and SSTR2 negative hemangioma." (PMID 41522408, 2025).
Hypertension (2 papers, 2023 to 2024). The presence of chronic increased pressure in the systemic arterial system. "The association with SSTR2, ASXL1, and ATOH1 may suggest potential novel mechanism in the pathogenesis of hypertension that needs to be to further elucidated." (PMID 37059828, 2023). "The SSTR2 gene (somatostatin receptor 2) has previously been suggested to be a candidate gene for hypertension but has not formally been linked to hypertension." (PMID 37059828, 2023). "Thus, the SSTR2, ATOH1 and ASXL1 genes are all novel hypertension candidate genes." (PMID 37059828, 2023).
intracranial meningioma (2 papers, 2021 to 2024). A meningioma that arises within the cranial cavity. "The strong expression of SSTR2 is well documented in intracranial meningiomas." (PMID 38919490, 2024).
liver cirrhosis (2 papers, 2013 to 2018). "In vivo, the up-regulated SSTR-2 in liver cirrhosis was inhibited by the addition of a selective COX-2 inhibitor, such as celecoxib." (PMID 30038293, 2018). "Hepatic SSTR-2 expression is up-regulated in subjects with liver cirrhosis." (PMID 30038293, 2018). "COX-2 may contribute to the up-regulation of hepatic SSTR-2 expression in subjects with liver cirrhosis." (PMID 30038293, 2018).
Lymphoepithelial Carcinoma (2 papers, 2022 to 2023). "Both lymphoepithelial carcinomas which were EBV-associated showed strong and diffuse expression of SSTR2." (PMID 35198446, 2022). "Both of our lymphoepithelial carcinomas, which were associated with EBV, showed strong and diffuse expression of SSTR2." (PMID 35198446, 2022). "A poorly differentiated squamous cell carcinoma with marked tumor infiltrating lymphocytes, morphologically reminiscent of a lymphoepithelial carcinoma but without EBV association also showed expression of SSTR2 in 90% of tumor cells." (PMID 35198446, 2022). "SSTR2 expression in TET, specifically lymphoepithelial carcinomas, squamous cell carcinomas, atypical carcinoid tumors, and small cell carcinomas may be a biomarker to identify patients who may respond to octreotide therapy." (PMID 35198446, 2022). "Interestingly, one of our study cases, a poorly differentiated thymic squamous cell carcinoma with marked lymphocytic tumor infiltrate at least suggestive of lymphoepithelial carcinoma but without EBV expression also showed strong and diffuse expression of SSTR2." (PMID 35198446, 2022).
lymphoma (2 papers, 2021). A malignant (clonal) proliferation of B- lymphocytes or T- lymphocytes which involves the lymph nodes, bone marrow and/or extranodal sites. "Therefore, it would be of high interest to study prognosis of lymphomas co-expressing SSTR2 and CXCR4 since the former seems to be a favorable and the latter an unfavorable biomarker." (PMID 34307181, 2021). "We observed SSTR2 and CXCR4 immunopositivity in DLBCL, FL and HL in approximately half of the patients and co-expression of both receptors in 38% of the three lymphoma subtypes." (PMID 34307181, 2021). "However, both SSTR2 and CXCR4 are commonly expressed in DLBCL, FL and HL rendering these lymphomas - when receptor positive - potential candidates for treatments targeting SSTR2/CXCR4." (PMID 34307181, 2021). "SSTR2, 3, 5 and CXCR4 IHC results in studied lymphoma subtypes." (PMID 34307181, 2021). "As a summary of these three and our own previous pilot study which all support current findings it is clear that SSTR2 and at least in HL also other SSTR subtypes are important for lymphoma growth but expression may be absent or low in a considerable number of cases." (PMID 34307181, 2021).
Meningothelial Meningioma (2 papers, 2021 to 2023). A WHO grade I meningioma characterized by the presence of tumor cells that form lobules. "Meningothelial meningioma WHO grade 1 and atypical meningioma WHO grade 2 showed significantly higher levels of SSTR2 than both transitional and fibrous subtypes (all Holm–Bonferroni adjusted pairwise p-values < 0.05)." (PMID 34830858, 2021).
non-small cell lung carcinoma (2 papers, 2014 to 2020). A group of at least three distinct histological types of lung cancer, including non-small cell squamous cell carcinoma, adenocarcinoma, and large cell carcinoma. "In the SSTR2-negative pancreatic and non-small lung cell cancer models of Zou and colleagues, re-expression of SSTR2 in the cancer cells led to significantly impaired tumor growth which was aggravated in a dose-dependent manner by application of octreotide and its derivate vapreotide (RC-160,)." (PMID 25010045, 2014). "Additionally, infection of pancreatic and non-small cell lung cancer cells with SSTR2 expressing adenoviral vectors significantly decreased tumor growth and proliferation rate." (PMID 25010045, 2014).
Obesity (2 papers, 2019 to 2020). Accumulation of substantial excess body fat. "Our in-vitro and in-vivo experiments show that proinflammatory, microbial and obesity-associated molecules cause a strong upregulation of SSTR2." (PMID 30609928, 2019). "We demonstrate for the first time that proinflammatory, microbial and obesity-associated molecules result in an SSTR2 upregulation." (PMID 30609928, 2019). "Furthermore, polymorphism in SSTR2 gene has been associated with obesity and food intake in the Mediterranean population." (PMID 32272767, 2020). "Most importantly, increased mRNA expression of SSTR2 has also been described in a diet-induced rat model of obesity." (PMID 32272767, 2020). "This in-vivo study revealed that obesity leads to an enhanced SSTR2 expression in gingival tissues, thereby supporting our in-vitro experiments with adipokines." (PMID 30609928, 2019). "Lastly, we also studied the effects of obesity on the SSTR2 expression in gingival biopsies in a rat diet-induced obesity model." (PMID 30609928, 2019). "Additionally, the SSTR2 expression was determined in gingival biopsies of rats with ligature-induced periodontitis, rats with diet-induced obesity, and periodontally and systemically healthy control animals." (PMID 30609928, 2019). "Therefore, the objective of the present study was to examine the regulation of SSTR2 in periodontal cells and tissues under inflammatory, microbial and obesity-related conditions." (PMID 30609928, 2019). "Furthermore, we studied possible effects of obesity on the SSTR2 expression in gingival biopsies in a rat diet-induced obesity model." (PMID 30609928, 2019). "First, we sought to analyze whether proinflammatory, microbial and obesity-related signals have an impact on the expression of SSTR2 in PDL fibroblasts." (PMID 30609928, 2019).
small cell carcinoma (2 papers, 2022 to 2024). A neuroendocrine carcinoma composed of small malignant cells which are often said to resemble "oat cells" under the microscope. "68Ga-DOTATATE PET scans (N=9) revealed a Krenning score of 3 in patients with atypical carcinoid tumor, small cell carcinoma, and squamous cell carcinoma (N=1 each) with SSTR2 expression in 95, 100, and 5% of tumor cells, respectively." (PMID 35198446, 2022).
Thymic Epithelial Tumors (2 papers, 2022 to 2025). "A study of 80 patients reported SSTR2 expression in 36.3% of thymic epithelial tumor cases, which had a direct relationship with younger age and reduced recurrence/metastasis-free survival." (PMID 41300989, 2025). "Histopathologic features and expression of SSTR2 in thymic epithelial tumors." (PMID 35198446, 2022).
vasculitis (2 papers, 2024 to 2025). "The literature has shown that pericytes and MPs are able to express SSTR2 in affected arteries in vasculitis of large vessels." (PMID 39457491, 2024).
adrenal tumors (1 paper, 2023). "Mariniello implied that SSTR1 and SSTR2 mRNA was expressed in 100% of adrenal tumors." (PMID 37185426, 2023).
Alzheimer disease (1 paper, 2019). A progressive, neurodegenerative disease characterized by loss of function and death of nerve cells in several areas of the brain leading to loss of cognitive function such as memory and language. "Somatostatin receptors (SSTRs) are also involved in some pathologies, such as Alzheimer’s disease, neuroendocrine dysfunctions and several types of cancer (mainly the SSTR2 subtype in the case of human tumors)." (PMID 31105551, 2019).
anaplastic gliomas (1 paper, 2015). "Within anaplastic gliomas, the median PFS for SSTR2-positive and SSTR2-negative HGGs was 21.3 versus 12.7 months, respectively." (PMID 25977882, 2015).
anaplastic meningioma (1 paper, 2025). A WHO grade III meningioma characterized by the presence of malignant morphologic features, including malignant cytology and a very high mitotic index (20 or more mitoses per ten high power fields). "Case 3 details a 79-year-old man with a recurrent spheno-orbital anaplastic meningioma who developed bilateral pulmonary metastases diagnosed by Ion robotic bronchoscopy and confirmed by neuropathology (SSTR2+, EMA focal+, PR+)." (PMID 41552249, 2025).